TLR3 (toll like receptor 3)
Diseases named in the same sentence as TLR3 in open-access papers (continued):
Sharing a sentence is not in itself a finding about the gene and the disease.
HCMV infection (continued). "Thus, pre-treatment of HFF with TLR3 and TLR4 ligands, but not TLR2 or TLR9 ligands, inhibited HCMV infection." (PMID 18053251, 2007).
Hypertension (15 papers, 2012 to 2025). The presence of chronic increased pressure in the systemic arterial system. "In TLR3-deficient mice, AngII-induced hypertension was abrogated suggesting the TLR3-TRIF pathway as crucial for a blood pressure increase in the AngII model." (PMID 33443617, 2021). "Differential transcription of four of these DEGs, which are known as associated with hypertension (F2r, Chi3l1, Ephx2, and Tlr3), was validated by qPCR." (PMID 32039698, 2019). "If placental TLR3/7/8 activation is sufficient to cause PE, then treatment of mice with TLR3/7/8 agonists should elicit endothelial dysfunction, proteinuria, and hypertension only if the animal is pregnant." (PMID 22848646, 2012). "We have previously reported that TLR3 activation with poly I:C in rats and mice causes systemic inflammation in both pregnant and non-pregnant animals, however only pregnant animals developed hypertension, proteinuria, and endothelial dysfunction." (PMID 22848646, 2012). "In addition to hypertension and endothelial dysfunction, we examined whether TLR3/7/8 activation during pregnancy caused other PE-like symptoms." (PMID 22848646, 2012). "Coronaviruses, adept at evading host antiviral pathways induced by viral dsRNA, appear to overactivate the TLR3-related pathway, potentially exacerbating damage to patients and promoting the development of cardiovascular complications, including hypertension." (PMID 41311551, 2025). "Our study suggests that the decreased level of TLR3 upon MS treatment can potentially reduce TLR3-mediated inflammatory signaling, vascular dysfunction, and hypertension." (PMID 40940770, 2025). "We reported that activation of toll-like receptor 3 (TLR3) via poly I:C (a synthetic double-stranded RNA viral mimetic) produces the PE-like symptoms of hypertension, endothelial dysfunction, and proteinuria in mice only when pregnant." (PMID 28993808, 2017). "Similar to TLR3 activation, TLR7/8 activation during pregnancy in mice caused pregnancy-dependent hypertension, endothelial dysfunction, splenomegaly, and an increased incidence of fetal demise." (PMID 22848646, 2012). "Nonetheless, excessive activation of placental TLR7/8 is sufficient to induce pregnancy-dependent hypertension and endothelial dysfunction similar to that induced by TLR3 activation." (PMID 22848646, 2012). "It has been reported that activation of TLR3 by double-stranded RNA can increase the inflammatory state and promote increased blood pressure and vascular dysfunction; hence, TLR3 can be a potential therapeutic target in treating hypertension." (PMID 40940770, 2025). "A previous study revealed that TLR3- TRIF signalling was activated in Ang II-induced hypertension, whereas TLR4-TRIF and TLR3-TRIF signalling was activated in Ang II-induced cardiac hypertrophy." (PMID 41552821, 2025). "A recent study has found that both TLR4-TRIF and TLR3-TRIF pathways mediate Ang II-induced cardiac hypertrophy, whereby only the TLR3-TRIF pathway is required for Ang II-induced hypertension." (PMID 37113698, 2023). "While TLR3-activated pregnant mice developed hypertension, TLR3 knockout mice induced with poly:IC did not, nor did levels of miR-210, HIF-1α and NF- κB increase significantly." (PMID 27529341, 2016). "P-PIC TLR3 KO mice did not develop hypertension and placental HIF-1α, NF-κBp50, miR-210, STAT6, and IL-4 levels were unchanged." (PMID 23844087, 2013). "Even though our normotensive P group consisted of women with chorioamnionitis, chronic hypertension, proteinuria without hypertension, or premature rupture of membranes, there were no placentas in this group that had increased levels of TLR3." (PMID 22848646, 2012). "Interestingly mice lacking in TLR3 (Tlr3−/−) did not develop elevated blood pressure upon angiotensin II infusion, indicating that TLR3-TRIF activation is a prerequisite for hypertension." (PMID 41311551, 2025).
ovarian carcinoma (15 papers, 2010 to 2025). A malignant neoplasm originating from the surface ovarian epithelium. "With respect to ovarian cancer, tumor cell expression of high levels of Toll-like receptor 3 (TLR3), a dsRNA-sensing receptor, has been associated with tumor progression." (PMID 30613350, 2018). "Combined chemotherapy/immunotherapy with TLR3 agonists using ventral water derived exosomes carrying tumor-associated antigens activates and amplifies antigen-specific T cell immunotherapy mechanisms against tumor-induced immunosuppression in advanced ovarian cancer." (PMID 36741380, 2022). "Several studies have demonstrated TLR3 expression in multiple neoplasia types including breast, prostate, and ovarian cancer." (PMID 33147700, 2020). "Toll-like receptor 3 (TLR3) was shown to play a dual role in ovarian cancer by eliminating tumor cells via upregulation of interferons and activation of natural killer cells and also by promoting cancer development." (PMID 33193718, 2020). "For example, a chemo/immunotherapy was established in advanced ovarian cancer by using TDEs and a Toll-like receptor 3 (TLR3) agonist." (PMID 28265569, 2017). "To conclude, the development of an ovarian cancer vaccine based on exosomes from the ascites fluid of ovarian cancer patients and the TLR3 agonist poly[I]:poly[C12U] (Ampligen®) is currently being prepared for phase I clinical testing." (PMID 26861303, 2016). "It has been reported that in situ stimulation of CD-40 and TLR-3 transforms ovarian cancer-infiltrating DCs from immunosuppressive to immunostimulatory cells." (PMID 24475147, 2014). "Researchers have hypothesized that exosomes in ascites combined with TLR3 stimulants might prolong progression-free survival in patients with high-grade ovarian cancer." (PMID 36741380, 2022). "Specifically for ovarian cancer, Zhou and colleagues have shown show that TLR2, TLR3, TLR4, and TLR5 are highly expressed on the normal ovarian epithelium, as well as on neoplastic ovarian epithelial cells." (PMID 22530148, 2012). "To investigate this, we decided to use the MyD88 negative A2780 human ovarian cancer cell line to stimulate it via TLR3." (PMID 22530148, 2012).
allergic disease (14 papers, 2012 to 2025). An immune response that occurs following re-exposure to an innocuous antigen, and that requires the presence of existing antibodies against that antigen. "Reports have also shown that respiratory epithelial cells produced interferon-β via TLR3 signaling in response to the invasive infection and allergy associated fungus, Aspergillus fumigatus." (PMID 23882263, 2013). "Varying the concentrations or treatment time course of TLR4 agonist could regulate TLR3-associated allergic inflammation for a new strategy to combat allergic diseases." (PMID 27826297, 2016). "In vivo trials highlight the role of TLR3 in upper airway allergic diseases, demonstrating that seasonal allergic rhinitis exacerbated by pollen exposure increases TLR3 mRNA expression and immunoreactivity in the nasal mucosa." (PMID 39988665, 2025). "Given that airway epithelium exposure to HDM has been linked with the TLR-3 gene expression down-regulation, it does not come as a surprise that the production of some anti-viral specific mediators becomes impaired in an allergy setting." (PMID 24498371, 2014). "The same pathways that mediate TLR3’s effects in the tumor microenvironment—particularly its ability to detect dsRNA and activate pro-inflammatory responses—also play crucial roles in non-malignant diseases, including infectious autoimmune disorders, and allergy." (PMID 39988665, 2025). "Finally, data presenting that FcεRI-mediated releasability of rPMCs might be modulated upon TLR3 ligation imply that dsRNA-type viruses may influence the severity of allergic reactions." (PMID 32185237, 2020). "The absence of TLR3 not only alleviates skin inflammation in allergic diseases, but also reduces the itch reflex in dry-skin-induced conditions." (PMID 39988665, 2025). "The TLR4 priming significantly increase expression of IL-6, IL-8, GM-CSF, IP-10, and RANTES in hTMSCs irrespective of allergy state, while the TLR3 priming did not significantly affect the secretion of these cytokines." (PMID 26376485, 2015). "TLR3 was involved in the pathogenesis of AD and ACD, so the up-regulation of let-7a-5p may play a role in the development of allergic diseases such as AD and ACD." (PMID 36685889, 2022).
head and neck cancer (14 papers, 2012 to 2025). A primary or metastatic malignant neoplasm affecting the head and neck. "Inhibition of NF-κB in head and neck cancer cell lines was associated with downregulation of TLR3 and decreased levels of IL-6 and IL-8 and the expected shift to a TH2 microenvironment, typical in head and neck squamous cell carcinomas did not occur." (PMID 25309546, 2014). "This study investigates the pro-tumorigenic role of TLR3, specifically its impact on CSCs in head and neck cancer." (PMID 40647457, 2025). "Despite the relatively evident tumor-suppressive roles of TLR1 and TLR3, controversies have been reported, such as the promoted tumor growth and cisplatin resistance observed in head and neck cancer cells as a result of activated TLR3 signaling." (PMID 36551308, 2022). "Stimulation of the TLR3-expressing OC2 cell line (a head and neck cancer cell line) with poly (I:C) can induce the phosphorylation of IRF3 and IκB, ultimately increasing the secretion of IL-6 and CCL5." (PMID 33986756, 2021). "The combination of cetuximab with either TLR3 or TLR8 stimulation induced increased NK-cell-mediated ADCC of head and neck cancer cells compared to cetuximab alone." (PMID 34681717, 2021). "For example, TLR3 resisted the DNA damage induced by cisplatin, which leads to the resistance of head and neck cancer cells to cisplatin." (PMID 34094905, 2021). "We therefore decided to assess the impact of TLR3 stimulation on the metabolic profile of the 4 head and neck carcinoma cell lines HONE1, FaDU, CNE1 and SQ20B cells using a metabolomics approach targeted on glucose metabolism pathways." (PMID 27791989, 2016). "In this study, a possible link between the innate immune recognition receptor TLR3 and metabolic reprogramming in Head and Neck carcinoma (HNC) cells was investigated." (PMID 27791989, 2016). "A strong and consistent expression of TLR3 has been reported not only in head and neck carcinoma, but in a variety of human cancers, such as melanoma, breast cancer, clear cell renal carcinoma and neuroblastoma." (PMID 27791989, 2016). "Head and neck cancer cell lines and OSCC tissue specimens were found to express TLR3, and this was associated with high levels of expression and activity of NF-κB." (PMID 25309546, 2014). "We demonstrate that TLR3 activation promotes stemness in head and neck cancer cell lines." (PMID 40647457, 2025). "To determine whether endogenous ligands released from head and neck carcinoma cells exposed to different stressors can activate TLR3, we used the HEKBlue-TLR3 reporter cell line (Invivogen)." (PMID 37894949, 2023). "For instance, triggering TLR3 could promote tumor growth and cisplatin resistance in head and neck cancer." (PMID 35000541, 2022). "TLR3 might contribute to the protection of cisplatin-induced DNA damage response leading to head and neck cancer development and cisplatin resistance." (PMID 36341390, 2022). "This article investigates the pro-tumorigenic role of Toll-like receptor 3 (TLR3) and its influence on cancer stem cells (CSCs) in head and neck cancer." (PMID 40647457, 2025). "However, in 8 other head and neck cancer cell lines (HEp2, SCC25, HSC2, HSC3, HSC4, SAS, HSQ89 and HO-1-u-1), poly (I:C)-stimulated TLR3 induced apoptosis in these cell lines though downregulating survivin expression." (PMID 33986756, 2021).
atherosclerosis (13 papers, 2011 to 2025). A disease characterized by the build-up of fatty material and calcium deposition in the arterial wall resulting in partial or complete occlusion of the arterial lumen. "In the cardiovascular system, TLR3 activation has been linked to atherosclerosis." (PMID 36723728, 2023). "Deficiency of TLR3 accelerates the onset of atherosclerosis in ApoE-/- mice." (PMID 21526997, 2011). "TLR3 has been implicated in mediating sterile pathologies in CVDs associated with immune responses, including pulmonary artery hypertension (PAH), atherosclerosis, myocardial infarction (MI), ischemia/reperfusion (I/R), and heart failure." (PMID 39828779, 2025). "TLR3 has been reported to show a protective role in mouse models of atherosclerosis and contribute to the ischemic preconditioning-induced protection against brain ischemia and attenuation of reactive astrogliosis." (PMID 36797783, 2023). "They showed that TLR3−/−ApoE−/− mice developed atherosclerosis earlier than TLR3+/+ApoE−/− counterparts, suggesting that TLR3 is a protective factor." (PMID 30225265, 2018). "Conversely, other studies have suggested that NOD2 and TLR3 have protective functions in vascular diseases, including atherosclerosis; indeed, we previously demonstrated such a function of NOD2 in arterial VSMCs." (PMID 29560100, 2018). "Early studies on TLR signalling in atherosclerosis have recently been supplemented by surprising effects exerted on arterial lesions, such as those mediated by the endosomal TLR3 and TLR7 receptors that are able to detect dsRNA and ssRNA, respectively." (PMID 23880853, 2013). "A different story unfolded from TLR3 in atherosclerosis—an endosomal TLR that signals via TRIF and is MyD88-independent." (PMID 23880853, 2013). "Additionally, 4 genes (Tnfsf15, Tlr3, Nlrp3, and Lepr), which have known roles in cholesterol efflux and atherosclerosis, were present in the network." (PMID 27239478, 2016). "It is also unknown what endogenous agonists of TLR3 may be involved in protection, as the genetic removal of TLR3 accelerates atherosclerosis and elastic lamina damage." (PMID 21526997, 2011). "New developments in the basic understanding of the roles of TLR3, TLR6 and TLR7 from in vitro studies and pre-clinical models of disease may open up new avenues of TLR-targeted therapy for atherosclerosis." (PMID 23880853, 2013).
schizophrenia (13 papers, 2016 to 2026). A major psychotic disorder characterized by abnormalities in the perception or expression of reality. "We selected these molecular targets because DISC1 is a well-known genetic risk factor for schizophrenia and it has been shown to be a target of TLR3/4 downstream signaling." (PMID 32477064, 2020). "On the flip side, studies on peripheral blood show downregulation of tlr3 and 5 mRNA levels and upregulation of il6 and il10 mRNA levels in patients with schizophrenia, which is in contrast to evidence from brain samples." (PMID 37627253, 2023). "For example, the activation of TLR-3 and pro-inflammatory cytokines such as IL-6 influence the development of schizophrenia-like behavior in adult offspring." (PMID 35963926, 2022). "In schizophrenia, increased TLR-3 and TLR-4 expression are observed on unstimulated monocytes and associated with an early age of onset." (PMID 36688057, 2022). "Activation of TLR3 leading to an upregulation of IL-1β, CCL2, and CXCL10 are also seen in models of autism and schizophrenia associated with white matter abnormalities." (PMID 33558485, 2021). "Another study using cultured neurons and mouse brain showed that TLR3 suppresses disrupted in schizophrenia 1 (Disc1) expression and consequently neuronal development." (PMID 31959813, 2020). "In addition to TLR4, activation of maternal TLR3, a viral receptor, resulted in altered behaviors including schizophrenia-like behaviors, deficit in exploratory and social behavior." (PMID 27445700, 2016). "Although TLR2 is shown to play a role in cognition, it would be incorrect to assume that it is the only pathway that might be involved in cognitive deficits in schizophrenia; other pathways or other TLRs such as TLR3 and TLR4 are involved with cognitive performance as well." (PMID 37627253, 2023). "MIA using polyriboinosinic-polyribocytidilic acid [poly(I:C)], a Toll-like receptor 3 agonist, has been widely used as an animal model for schizophrenia since adult offspring after prenatal poly(I:C) exposure show behavioral abnormalities relevant to schizophrenia." (PMID 34977960, 2022). "The genes HGF, PRRT2, EGR1, EGR3, C11orf87, TLR3 and PLEKHH2 have been reported in either genetic analysis or gene expression analysis of schizophrenia, and were all upregulated in fibroblasts from patients in our study." (PMID 31959813, 2020). "Drug-naïve patients with schizophrenia exhibited increased TLR4 mRNA levels and unaltered TLR3 mRNA levels in peripheral blood mononuclear cells (PBMC), alongside elevated TLR4 and TLR8 mRNA levels and reduced TLR3 mRNA levels in white blood cells compared to healthy controls." (PMID 38792602, 2024). "NF-κB was evaluated because the TLR3/4-dependent regulation of NF-κB is potentiated when WDFY1 is over-expressed and NF-κB is a core neuroinflammatory molecule involved in the pathogenesis of schizophrenia." (PMID 32477064, 2020). "Interestingly, TLR3 has been shown to regulate the expression of DISC1 (from Disrupted in schizophrenia 1) in neurons, directly linking this signaling pathway to schizophrenia." (PMID 32477064, 2020).
colon cancer (12 papers, 2008 to 2025). "To further confirm that TLR3 is the reovirus recognizing receptor for HCT116 colon cancer cell line, we next down regulated TLR3 in the cell line using small interfering (si) RNA followed by reovirus treatment at dose of 5 MOI for 48 hours." (PMID 28422714, 2017). "We thankfully acknowledge John Mariadason of Ludwig Institute for Cancer Research, Melbourne, Australia for sharing the RNA transcriptome data to analyze the expression of TLR3 in 56 colon cancer cell lines." (PMID 28422714, 2017). "Hence, we examined the TLR3 mRNA levels in lung, liver, breast and colon cancer cells." (PMID 28427199, 2017). "In conclusion, FGFR4 in cancer cells promotes CXCL10 production via TLR3-IRF-IFNβ-dependent signaling that subsequently induces CAF differentiation and activation, culminating in colon cancer progression." (PMID 40447617, 2025). "TLR2, TLR3, and TLR4 are overexpressed in most colon cancer cells." (PMID 40143078, 2025). "Interestingly, although engagement of TLR3 expressed in human breast tumor cells induces massive apoptosis, triggering TLR4 in murine colon cancer MC26 cell line leads to immune evasion mediated by the inhibition of T- and NK-cell activities." (PMID 24155891, 2013).